STAT3 (signal transducer and activator of transcription 3)
Diseases named in the same sentence as STAT3 in open-access papers (continued):
Sharing a sentence is not in itself a finding about the gene and the disease.
cancer (continued). "Growing evidence indicates that the signaling proteins of EPHA3 downstream, including PI3K, BMX and STAT3, play crucial roles in tumorigenesis and cancer progression." (PMID 27101199, 2016). "We found a significant inverse correlation between FOXD3 protein levels and phosphorylated STAT3 (Tyr705) protein levels in nuclear extracts of clinical cancer samples obtained from patients who regularly used aspirin." (PMID 26898989, 2016). "The signal transducer and activator of transcription 3 (STAT3) is a key downstream effector oncogene activated in several cancer types proven to be a promising target for cancer treatment." (PMID 27827876, 2016). "On the contrary, in immune cells, NF-κB and STAT3 control the expression of other cytokines and inflammatory/immune mediators that mediate NF-κB and STAT3 activation in cancer cells, including IL-1, IL-6, and TNFα." (PMID 27602766, 2016). "Deregulated signal transducer and activator of transcription 3 (STAT3) signaling has been well documented in certain cancers." (PMID 26768588, 2016). "It is believed that p-STAT3 modulates apoptosis in cancer cells and cleaved caspase-3 levels, which is a marker of apoptosis." (PMID 27052330, 2016). "In cancer patients, MDSCs isolated from different anatomical compartments were shown to have high levels of phosphorylated STAT3 that correlated with ARG1 expression, a downstream target of activated STAT3." (PMID 26700461, 2016). "STAT3 and NF-κβ are well known molecules involved in both macrophage differentiation into the M2 phenotype and cancer progression." (PMID 27404320, 2016). "STAT3 is a transcription factor that plays important roles in the development and progression of many cancers." (PMID 26743134, 2016). "In this study, we identified p70S6K activation by IL-6 located downstream of the PI3K/Akt/mTOR, MAPK/ERK, and JAK/STAT3 signaling pathways, which were the most important survival pathways that promote most cancers." (PMID 27174914, 2016). "The lysine acetylation of STAT3 is of key importance in the DNA-binding and the transcription for the oncogenic activity which is related to many cancers such as pancreatic cancer." (PMID 27183223, 2016). "The constitutive phosphorylation of STAT3 on tyrosine 705 residues (p-STAT3Y705) is found in a wide variety of human cancer cells." (PMID 27074565, 2016). "Two Stat3 signaling target genes, c-Myc and Klf4, play critical roles in cancer stem cell self-renewal." (PMID 27460364, 2016). "IL-6 signaling has been implicated in various cancers, as the IL-6 receptor complex is linked to JAK activity targeting STAT3." (PMID 26849807, 2016). "The results show that apoptosis in cancer cells was decreased when p-STAT3 expression was increased, and vice versa." (PMID 27052330, 2016). "Together, these results strongly suggest that LIF upregulates miR-21 through the STAT3 signaling pathway to promote EMT in cancer cells." (PMID 26716902, 2016). "Microtubule inhibitors have been shown to inhibit Janus kinase 2/signal transducer and activator of transcription 3 (JAK2/STAT3) signal transduction pathway in various cancer cells." (PMID 27367272, 2016). "Intriguingly, A549 and H1975 cells exhibited increased p‐STAT3, which primarily mediates pro‐survival and proliferative signaling in cancer cells." (PMID 27241841, 2016). "The levels of ERK1/2, AKT and STAT3 proteins that promote cancer progression were reduced by simvastatin, a finding that correlated with a loss of cell viability and with apoptosis." (PMID 26735890, 2016). "The JAK2/STAT3 pathway regulates not only the anti-apoptotic survival signal but also the motility of cancer cells." (PMID 27012679, 2016). "ROS also modulate STAT activation in normal and cancer cells, and in turn, STAT3 and STAT5 modulate ROS production." (PMID 27513743, 2016). "Constitutively activated STAT3 per se has been shown to be able to function as an oncogene, and STAT3 has been widely accepted as a cancer therapeutic target." (PMID 26701727, 2016).
cancer (continued). "Recent evidence further suggest that feedback activation of STAT3-signaling plays prominent role in mediating drug resistance to a broad spectrum of anti-cancer therapies, and IL6/STAT3 pathway inhibitors can serve as effective means to eradicate CSCs." (PMID 31656694, 2016). "It has been shown that constitutive activation of STAT3 induces proliferation and invasion of cancer cells via activation of several downstream target genes such as c-Myc and MMP9." (PMID 27824155, 2016). "STAT3 also regulates self-renewal in cancer stem cells by systematically regulating canonical stemness genes including Nanog, Sox2, Oct4 and myc." (PMID 27472461, 2016). "The roles of STAT3 signaling in suppressing apoptosis and autophagy in cancer cells have been well documented." (PMID 27716625, 2016). "The role for STAT3 in carcinomas remains controversial - nuclear STAT3 (pYSTAT3) is regarded as a biomarker for prognosis prediction in solid tumours." (PMID 27191495, 2016). "The signal transducer and activator of transcription protein 3 (STAT3) is a latent cytosolic transcription factor that is aberrantly activated in many cancers, including NSCLC." (PMID 25674792, 2015). "Hyperactivation of signal transducer and activator of transcription 3 (STAT3) has been observed in many types of cancers." (PMID 25331984, 2015). "The growth of human GBM cell lines and their TMZ resistance has been inhibited by RNA based knockdown and by small molecule inhibition of STAT3, a latent transcription factor that is dysregulated in many cancers." (PMID 26283544, 2015). "STAT3 activation is able to directly affect the expression of IL-6, which is also one of the key STAT3 activators during cancer EMT progression." (PMID 25788270, 2015). "Here, we discuss these properties in the light of potential connections between STAT3-driven alterations of mitochondrial metabolism and the development of drug resistance in cancer patients." (PMID 26106584, 2015). "STAT3 is an oncogene, which is constitutively activated in multiple types of human cancers and contributes to cancer progression." (PMID 25961376, 2015). "The molecular functions of p-STAT3 in malignant tumors, mainly including its influence on cell cycle, inflammatory process and angiogenesis, have been extensively discussed in the recent years." (PMID 26024373, 2015). "Signal transducer and activator of transcription 3 (STAT3) can also promote IL-6 production in serum-starved cancer cells." (PMID 26087456, 2015). "Overexpression of Stat3 has been observed in various cancer tissues including HNSCC as well as in NPC." (PMID 25607111, 2015). "As the list of human tumors that harbor constitutive STAT3 activity grows, there is an increasing chance that many more cases of human cancers will be identified in which STAT3 has a prominent role in induction and/or maintenance of the oncogenic phenotype." (PMID 26464811, 2015). "Inhibition of STAT3 has been validated in vitro and in vivo as a promising therapeutic avenue for cancer treatment, and several molecules have been identified to block STAT3 activation." (PMID 26314961, 2015). "Recent studies have suggested that antiapoptotic genes Bcl-2, Bcl-xL, Mcl-1 and angiogenic gene VEGF are regulated by STAT3 in various cancers." (PMID 26551008, 2015). "Along with inhibition of mTOR signaling, there are several mechanisms proposed for anti-cancer effects of metformin including STAT3 inhibition leading to induction of apoptosis and effects on cancer-related miRNAs." (PMID 26284586, 2015). "Functional experiments have shown that inhibition of miR-155 induces elevated SOCS1 expression and the subsequent suppression of STAT3 in various cancers." (PMID 25823817, 2015). "Studies on human cancer cells have shown that KYN activates the AhR-ARNT associated transcription of IL-6, which induced autocrine activation of IDO1 via STAT3." (PMID 26881062, 2015).
cancer (continued). "The importance of the IL-6/Stat3 signaling in cancer and cancer stem cells has been well documented." (PMID 26376676, 2015). "This was achieved by influencing the JAK/STAT3 signaling pathway and inhibiting several kinase cascades involved in the metastasizing of cancer cells." (PMID 26457112, 2015). "As one of the STAT family members, STAT3 is correlated with positive regulation of cell growth and highly activated in cancer cells." (PMID 26464811, 2015). "The pooled hazard ratios (HRs) with 95 % confidence intervals (95 % CIs) of overall survival (OS) and disease-free survival (DFS) were used to assess the prognostic role of p-STAT3 expression level in cancer tissues." (PMID 26024373, 2015). "This group proposed that targeting IL6/STAT3 to inhibit cancer stem cell function has important therapy implications for the treatment of HCC." (PMID 26074923, 2015). "Elevated STAT3 activity has been observed in many spontaneous and experimentally established mammalian cancers, which demonstrates its critical role in tumorigenesis." (PMID 26464811, 2015). "Among the STAT proteins, STAT3 stands out as the most attractive one in relation to its contributions to development and progression in numerous forms of cancer, including OS." (PMID 26783521, 2015). "A significant activation of p-STAT3 expression was observed in the cancer group compared to the naive group; however, intrathecal administration of BE did not inhibit the activation of p-STAT3 in the cancer group." (PMID 26649065, 2015). "Role of STAT3 in induction and maintenance of an inflammatory microenvironment during initiation and progression of cancer is well documented." (PMID 25868978, 2015). "Cumulative evidence supports activation of Stat3 as an oncogenic pathway in many cancers, including RCC." (PMID 26625308, 2015). "We further confirmed that inhibition of the STAT3 pathway by STAT3-specific shRNA or LY5 sensitized K-Ras mutated cancer cells to MEK inhibitor treatment in vitro and in vivo." (PMID 25961376, 2015). "Constitutive activation of IL-6/STAT3 signaling has been detected in a wide variety of human cancers and is considered as an important factor for cancer initiation, development, and progression." (PMID 26417930, 2015). "This is particularly relevant in the context of inflammation-induced cancer, where STAT3 is known to play a major role, consistent with the observation that persistent IL-6 production and STAT3 activation are prominent features of chronic inflammation." (PMID 26106584, 2015). "In contrast to normal cells, where activation of STAT3 is tightly regulated and transient, STAT3 is frequently constitutively activated in cancer cells." (PMID 25928246, 2015). "In accordance with the functional experiments, AMD3100 decreased CMLE_IR-induced Akt and STAT3 pathway activation; a minor impact on pERK was observed in the cancer cells exposed with CMLE_IR + AMD3100 compared to CMLE_IR alone." (PMID 26396176, 2015). "Validating this, the activation level of STAT3, as marked by p-Tyr705, particularly in the mitochondria, was significantly higher in Bcl-2-overexpressing cancer cells." (PMID 26430964, 2015). "In conclusion, we have identified a novel signaling network, the miR-197/CKS1B/STAT3 axis, which regulates cancer progression in chemoresistant NSCLC." (PMID 25597412, 2015). "Altogether these data show, for the first time, that IL-27 induces IDO and PD-L1 expression in human EOC cancer cells through activation/phosphorylation of STAT1 or STAT3, respectively." (PMID 26657115, 2015). "This is consistent with the previous findings that both metformin and aspirin inhibited the transcriptional activation of STAT3 in various cancer cell lines." (PMID 26056043, 2015). "Consistent with this conclusion are reports that S727 phosphorylation of mitochondrial STAT3 is required for the oncogenic growth of cancer cells." (PMID 26664907, 2015).
cancer (continued). "IL-6 contributed to upregulation of genes related to CSCs and cell proliferation as well as activation of JAK2/STAT3 in cancer cells." (PMID 25797257, 2015). "We further demonstrated that a novel signaling pathway, the miR-197/CKS1B/STAT3 axis, has the ability to promote cancer progression in chemoresistant NSCLC." (PMID 25597412, 2015). "Nuclear localized STAT3 dimer binds to the promoters of various target genes and regulates their transcriptions, which are involved in cancer cell proliferation, survival and invasion." (PMID 25849286, 2015). "This study uncovered a new strategy to specifically inhibit the STAT3-mediated signaling and provided a novel STAT3 inhibitor for potential cancer treatment." (PMID 26010889, 2015). "Given the wide role of STAT3 in cancer, miRNAs can be potentially considered as new therapeutic approaches for future research." (PMID 26464811, 2015). "Cancer increased liver STAT-3 phosphorylation approximately 2-fold, which coincided with a significant 20% reduction (p = 0.002) in liver albumin protein concentration." (PMID 25789991, 2015). "Aberrant IL-6-Jak-STAT3 signaling in cancer cells has also emerged as an important mechanism for cancer initiation, development and progression." (PMID 26501341, 2015). "Identification of small molecules directly targeting STAT3 has been a well-recognized strategy for treating cancer, particularly the cancer cells with constitutively activated STAT3." (PMID 26010889, 2015). "Recently, Yang revealed that high invasive OVCA cells were strongly glutamine dependent, and glutamine was a key mitochondrial substrate for driving cancer metastasis by induction of STAT3 serine phosphorylation." (PMID 25947346, 2015). "Previous reports had mentioned Curcumin, in a dose dependent manner to suppress STAT3 phosphorylation and concomitant decrease in proliferative capacity in cancer derived cells." (PMID 25822711, 2015). "NF-κB/RELA and STAT3 potentially partner in transcriptional regulation of tumorigenic genes in cancer cells." (PMID 26046794, 2015). "The protein levels of phosphorylated JAK2 and STAT3 in cancer cells were increased upon co-culture with ADSCs." (PMID 25797257, 2015). "Leptin exposure increased cancer cell migration/invasion through leptin-mediated activation of JAK/STAT3, PI3/AKT and RhoA/ROCK and promoted new lamellipodial, stress-fiber and focal adhesion formation." (PMID 26053184, 2015). "STAT3 is hyper-activated by constitutive phosphorylation of tyrosine 705 (Y705) in many cancer types, including HNSCC." (PMID 26267899, 2015). "c-Myc, Bcl-2 and survivin are well known cancer promoter genes and their transcription can be triggered by STAT3, Notch and Wnt signaling, respectively." (PMID 25896424, 2015). "To further explore the exact mechanism by which Eag1 regulates the VEGF expression levels, we focused on STAT3 which contributes to cancer development and progression in numerous forms of cancers including OS." (PMID 26783521, 2015). "Decreased expression of SOCS proteins through promoter methylation significantly contributes to the persistent tyrosine phosphorylation of STAT3 in cancers, as well as in CCA." (PMID 26485275, 2015). "This activity contributes to STAT3 pro-oncogenic functions, since it is required for survival and in vivo growth of STAT3-addicted human cancer cell lines, which also display low but constitutive Y-P STAT3." (PMID 26106584, 2015). "Among the STAT family, STAT3 is an oncogenic protein and its constitutive activation is highly relevant to cancers." (PMID 26166037, 2015). "In all the cases, IL-6R was detected in the cytoplasm and cytomembrane of almost all residual cancer cells, while p-STAT3 was expressed only in the outer layers of the cancer nest." (PMID 25761055, 2015). "Conversely, chronic activation of STAT3 signaling is frequently detected in numerous human inflammatory diseases and cancer, including gastric tumorigenesis." (PMID 26417930, 2015).
cancer (continued). "As a non-receptor tyrosine kinase, ETK activation/expression is required for STAT3 activation in cancer cells." (PMID 25849286, 2015). "Much evidence has revealed the central cancer-promoting role of STAT3, thereby making it an ideal target for cancer therapy." (PMID 26631279, 2015). "Others have previously demonstrated that GIV positively autoregulates its own transcription by enhancing STAT3 activation via its GEF motif in invasive cancer cells." (PMID 26524953, 2015). "Persistent activation of STAT3 has been observed in approximately 70% of cancers and is believed to regulate TIC activity." (PMID 26314961, 2015). "Other studies have reported that cancer cells promoted EMT by activating the STAT3 signaling pathway." (PMID 26440411, 2015). "When STAT3 is found in the mitochondria enhances oxidative phosphorylation, encouraging the growth of cancer cells when over-expressed." (PMID 25915429, 2015). "As a result, STAT3 has been correlated with positive regulation of cell growth and is highly activated in cancer cells." (PMID 26464811, 2015). "Transcriptional silencing of SHP-1 plays a critical role in the development and progression of cancers through STAT3 activation." (PMID 26547689, 2015). "STAT3 is frequently activated in various cancers and plays a crucial role in enhancing EMT and increasing invasiveness outside the CNS." (PMID 25638155, 2015). "Recently, some evidence has also indicated that HDAC inhibitor suppression of JAK2/STAT3 signaling in cancer cells occurs through inducing the acetylation of histones connected to the promoter of SOCS3, a potent feedback inhibitor of JAK2/STAT signaling." (PMID 26636769, 2015). "Some studies have proposed that cucurbitacins induce inhibitory effects against several human cancer cell lines via suppression of STAT3 phosphorylation." (PMID 25674792, 2015). "The SDF-1α/CXCR4 biological axis can activate multiple intracellular signaling pathways, including the FAK, AKT, ERK1/2, P38, STAT3, mTOR, and Wnt/β-catenin signaling pathways in various cancers." (PMID 25609203, 2015). "HER family pathway activation (p-erbB2, p-EGFR, p-HER3) was common in the primary and MBC samples, with downstream activation of p-mTOR and p-STAT3 seen in several patients’ cancers." (PMID 25871911, 2015). "Meanwhile, high STAT3 expression and STAT3 signal activated have be reported in many cancers, and its expression generally received a worse prognosis in terms of both PFS and OS." (PMID 26389681, 2015). "As a consequence, STAT3 inhibitors should be worth evaluating as a therapeutic option for cancer patients who develop cachexia." (PMID 25460504, 2015). "STAT3 regulates cell-cycle progression and apoptosis, plays a key role in oncogenesis, and is aberrantly expressed in cancer cells." (PMID 26199948, 2015). "These pathways converge in autocrine or paracrine phosphorylation of STAT3, making IL-6 a key contributor to tumor growth, drug resistance, induction of cancer stem cells, and metastasis." (PMID 26512918, 2015). "Of note, the miR we found concomitantly deregulated in DC upon exposure to gp120 have been previously reported to belong to a regulatory loop contributing to STAT3-mediated cancer development." (PMID 26116514, 2015). "This suggests that STAT3 induces a characteristic set of gene expression changes in HER2-positive cancers." (PMID 26234940, 2015). "Activated STAT3 in cancer cells can ensure constitutive NF-κB activation, even when the IKK complex is only temporarily activated." (PMID 26474284, 2015). "In this context, recent reports indicated that AURKA overexpression promotes activation of NF-κB and STAT3 pathways in these cancers." (PMID 25987188, 2015). "Our study not only uncovered a new compound and a new method to treat cancer, but also introduced a new tool to study the function of STAT3 and a new strategy to inactivate proteins in general." (PMID 26010889, 2015).